RN7SL516P (RNA, 7SL, cytoplasmic 516, pseudogene)
Gene: Miscellaneous RNA gene on chromosome 2 (29,681,027 to 29,681,323, reverse strand). Ensembl gene ENSG00000242699.
Homologues: Orthologues: chimpanzee Metazoa_SRP (99% identical), macaque Metazoa_SRP (94% identical). Paralogues in human: RN7SL1 (83% identical), RN7SL2 (83% identical), RN7SL655P (82% identical), RN7SL127P (81% identical), RN7SL125P (81% identical), RN7SL14P (81% identical), RN7SL3 (81% identical), RN7SL45P (81% identical), RN7SL712P (81% identical), RN7SL7P (81% identical), RN7SL230P (80% identical), RN7SL296P (80% identical), and 703 more.